TP63 (tumor protein p63)
Description:
Acts as a sequence specific DNA binding transcriptional activator or repressor. The isoforms contain a varying set of transactivation and auto-regulating transactivation inhibiting domains thus showing an isoform specific activity. Isoform 2 activates RIPK4 transcription. Involved in Notch signaling by probably inducing JAG1 and JAG2. Plays a role in the regulation of epithelial morphogenesis. The ratio of DeltaN-type and TA*-type isoforms may govern the maintenance of epithelial stem cell compartments and regulate the initiation of epithelial stratification from the undifferentiated embryonal ectoderm. Required for limb formation from the apical ectodermal ridge. Activates transcription of the p21 promoter. Binds to an upstream regulatory region of the DSG1 gene and promotes transcription.
Synonyms: p63; p73L; KET; P73H; TP73L; p51; SHFM4; EEC3; OFC8; NBP; p53CP; p40; AIS; B(p51A); B(p51B); LMS; RHS; TP53CP; TP53L
Tractability: Small molecule: a structure with a bound ligand is known. PROTAC: UniProt records ubiquitination sites on it; ubiquitination databases record sites on it.
Gene: Protein-coding gene on chromosome 3 (189,631,389 to 189,897,276, forward strand). Ensembl gene ENSG00000073282.
Subcellular location: Nucleus
Subcellular location (Human Protein Atlas): Nucleoplasm
Pathways (Reactome):
Developmental Biology: Developmental Lineage of Mammary Gland Luminal Epithelial Cells; Developmental Lineage of Mammary Gland Myoepithelial Cells; Developmental Lineage of Mammary Stem Cells; Differentiation of Keratinocytes in Interfollicular Epidermis in Mammalian Skin
Programmed Cell Death: Activation of PUMA and translocation to mitochondria; Pyroptosis
Gene Ontology:
Molecular function: DNA-binding transcription factor activity; identical protein binding; MDM2/MDM4 family protein binding; protein binding; sequence-specific DNA binding; WW domain binding; DNA binding; DNA-binding transcription factor activity, RNA polymerase II-specific; promoter-specific chromatin binding; RNA polymerase II cis-regulatory region sequence-specific DNA binding; chromatin binding; damaged DNA binding; DNA-binding transcription activator activity, RNA polymerase II-specific; double-stranded DNA binding; protein domain specific binding; transcription cis-regulatory region binding
Biological process: negative regulation of DNA-templated transcription; positive regulation of DNA-templated transcription; positive regulation of fibroblast apoptotic process; positive regulation of Notch signaling pathway; positive regulation of osteoblast differentiation; positive regulation of transcription by RNA polymerase II; apoptotic process; establishment of skin barrier; positive regulation of apoptotic signaling pathway; regulation of apoptotic process; regulation of epidermal cell division; DNA damage response; negative regulation of intracellular estrogen receptor signaling pathway; positive regulation of cell differentiation; positive regulation of cell population proliferation; positive regulation of somatic stem cell population maintenance; protein tetramerization; regulation of DNA-templated transcription; spermatogenesis
Cellular component: chromatin; cytoplasm; nucleoplasm; nucleus; transcription regulator complex; dendrite; protein-containing complex
Genetic constraint (gnomAD): Loss-of-function variants: 17 observed, 86.02 expected, observed/expected ratio (o/e) 0.2, 90% interval 0.13 to 0.3. The upper end of that interval is the gene's LOEUF score, 0.3, which puts it in group 1 of 6, group 1 being the genes least tolerant of losing a copy. Missense variants: 648 observed, 944.14 expected, observed/expected ratio (o/e) 0.69, 90% interval 0.64 to 0.73. Synonymous variants: 330 observed, 340.85 expected, observed/expected ratio (o/e) 0.97, 90% interval 0.88 to 1.06.
Gene-disease validity (ClinGen):
ClinGen rates the evidence that TP63 causes each of these diseases.
ectrodactyly, ectodermal dysplasia, and cleft lip-palate syndrome 3 (autosomal dominant): Definitive. Any EEC syndrome in which the cause of the disease is a mutation in the TP63 gene.
Cancer hallmarks: invasion and metastasis (suppresses); escaping programmed cell death (suppresses); proliferative signalling (promotes)
Homologues: Orthologues: chimpanzee TP63 (100% identical), macaque TP63 (99% identical), pig TP63 (99% identical), rabbit TP63 (98% identical), dog TP63 (98% identical), guinea pig TP63 (98% identical), mouse Trp63 (98% identical), rat Tp63 (98% identical), tropical clawed frog tp63 (84% identical), zebrafish tp63 (65% identical). Paralogues in human: TP73 (54% identical).
Diseases named in the same sentence as TP63 in open-access papers:
TP63 is named in the same sentence as 198 diseases in open-access papers, as found by Europe PMC text mining. Sharing a sentence is not in itself a finding about the gene and the disease. The quoted sentences say what the papers report.
squamous cell carcinoma (68 papers, 2001 to 2025). A carcinoma arising from squamous epithelial cells. "Further, TP63 is frequently amplified in squamous cell carcinoma, and increased TP63 has been linked to YAP activation and alteration of TEAD binding." (PMID 37150829, 2023). "TP63 (tumor protein p63) was associated with the proliferation, migration, colony formation, and invasion of certain squamous cell carcinomas (SCCs)." (PMID 35807355, 2022). "Although p63 and p73 are rarely mutated in cancer, TP63 is situated within the locus frequently amplified in squamous cell carcinoma." (PMID 34207603, 2021). "Interestingly, the rare TP63 mutations reported in squamous cell carcinoma are located in the TA domain, suggesting that inhibition of TAp63 isoform expression might favor tumor development." (PMID 31159154, 2019). "For instance, in squamous cell carcinoma, TP63 and SOX2 activate the enhancer of EGFR, further stimulating the MEK/ERK1/2 and PI3K/AKT signaling." (PMID 40032852, 2025). "TP63 is characteristic in squamous cell carcinomas and, if TP63 protein is combined with SOX2 it is known to promote LUSC progression and serve as super-enhancers in squamous tumors." (PMID 40223089, 2025). "TP63 has been extensively studied and is known to play a pivotal role in squamous cell carcinoma by regulating genes involved in proliferation and survival." (PMID 41323280, 2025). "In detail, TP63 is frequently amplified or overexpressed in squamous cell carcinomas (SCCs) of the head and neck, skin, lung and esophagus." (PMID 39201428, 2024). "TP63 acts as a lineage survival oncogene in squamous cell carcinoma and is involved in the differentiation of keratinocytes and the development of squamous cells." (PMID 39234254, 2024). "TP63 can induce the expression of various proteins using different promoters or splicing, DNA-binding or functioning through their transactivation in squamous cell carcinoma (SCC), lung cancer and other cancer types." (PMID 37047552, 2023). "The 3q amplicon contains key oncogenic driver genes such as TP63, SOX2, PIK3CA, which are implicated in all squamous cell carcinomas, including ESCC." (PMID 37444412, 2023). "TMTC3 was abnormally highly expressed in squamous cell carcinomas (SCCs), and regulated by TP63, an SCCs-specific transcription factor." (PMID 35982901, 2022). "Here, we identify for the first time an RBP that controls the balance between different splice isoforms of TP63, a key gene involved in squamous cell carcinoma and especially HNSCC." (PMID 36970727, 2022). "A large number of studies have reported that TP63 can be used as a prognostic factor for cancers such as salivary gland adenoid cystic carcinoma, anaplastic large cell lymphoma, and squamous cell carcinoma." (PMID 35480110, 2022). "As the main isotype of the transcription factor TP63 expressed in squamous cell carcinoma, ΔNp63α played a tumor-promoting effect in squamous cell carcinoma by regulating the expression of different target genes." (PMID 34930262, 2021). "In the development of squamous cell carcinoma, TP63 plays an important role in chromatin remodeling and enhancer reprogramming and epidermal differentiation." (PMID 34168974, 2021). "TP63 gene amplification and corresponding protein overexpression have been so far documented mainly in squamous cell carcinoma and related to the tumour proliferation fraction." (PMID 33273537, 2020). "Co-amplification of SOX2 and TP63 is often observed in squamous cell carcinomas which further validate our findings." (PMID 32974170, 2020). "IRF6 regulated by TP63 plays a tumor suppressor role in squamous cell carcinomas through a Notch-dependent mechanism, which plays critical roles in EMT pathway." (PMID 33156825, 2020). "Recent studies have proved that IRF6, regulated by TP63, plays a tumor suppressor role in squamous cell carcinomas through a Notch-dependent mechanism." (PMID 31019894, 2019).
squamous cell carcinoma (continued). "IRF6 was reported to be positively regulated by TP63 in squamous cell carcinomas and normal skin tissues." (PMID 31019894, 2019). "TP63 is frequently expressed in squamous cell carcinomas of the lung, head and neck region, and esophagus." (PMID 28258440, 2017). "TP63 has also been shown to be expressed in cervical cancer and interacts with SOX2 in squamous cell carcinomas we also stained for TP63 protein in parallel sections from the same biopsies." (PMID 25531390, 2014). "These canonical activities can be repressed by TP63 in normal stratifying epithelia to maintain proliferative capacity or drive proliferation of squamous cell carcinomas, where TP63 is frequently overexpressed/amplified." (PMID 24823795, 2014). "Genes associated with squamous cell cancer, KRT5, cystatin A (CSTA) tumor protein p63 (TP63) and SOX2, were expressed at higher levels in ASC, but also expressed to some extent in the AC." (PMID 24324581, 2013). "Indeed, computational analysis of the chromatin data have proposed a critical role of the TP63 transcription factor in the differentiation and development of human squamous cell carcinoma." (PMID 41323280, 2025). "Notably, we identified a malignant cell subpopulation expressing high levels of the key oncogenic driver gene TP63 in squamous cell carcinoma, known as TP63+ SLC7A5+ HNSCC." (PMID 39234254, 2024). "Overexpression of TP63 was reported in other squamous cell carcinomas, including ESCC." (PMID 37444412, 2023). "Co-amplification of genes SOX2 and TP63 is uniquely seen in squamous cell carcinomas." (PMID 37444412, 2023). "KRT5 and TP63 are known as the squamous cell carcinoma (SCC) of the lung-specific genes." (PMID 35584089, 2022). "In squamous cell carcinomas (SCCs), the SCC-specific SE region co-occupied by TP63 and SOX2 enhances seRNA CCAT1 (colon cancer associated transcript 1) transcription, and the TP63/SOX2/CCAT1 complex promotes tumorigenesis by activating EGFR (epidermal growth factor receptor) transcription." (PMID 35461306, 2022). "The transcription factors (TP63, SOX2) implicated in homeostasis of epithelial differentiation were found to be abnormally expressed in squamous carcinoma, and cell cycle, death, nuclear factor‐κB and other oncogenic pathways related to the development of squamous carcinoma." (PMID 32536035, 2020). "Furthermore, amplification of TP63 was also commonly found in squamous cell carcinomas of lung, and neck and head which showed over-expression in these tumors." (PMID 32617189, 2020). "Therefore, the dysregulation of TP63 is closely related to the occurrence of squamous cell carcinoma (Romano, Solomon & Sinha, 2012)." (PMID 31938577, 2020). "Moreover, numerous investigations confirmed the upregulation of expression of ΔNp63α, the predominant TP63 isoform in squamous epithelium, in squamous cell cancers, including head and neck, skin, as well as the lung." (PMID 31877723, 2019). "Squamous cell carcinoma biomarkers such as TP63 (tumor protein p63), CK5/6 (cytokeratin 5/6), 34βE12 (high molecular weight cytokeratins) could also be identified in adenocarcinoma." (PMID 29137182, 2017). "Moreover, TP63 overexpression was characteristically observed in squamous cell carcinomas of the lung, esophagus, and head and neck region." (PMID 28258440, 2017). "Furthermore, a quantitative approach that is based on a weighted algorithm of the expression of five proteins is better at classifying NSCLC NOS into squamous cell carcinoma or adenocarcinoma than TTF1/TP63 staining." (PMID 21785682, 2011). "Therefore, TP63 could be used as a valid marker for squamous cell carcinoma histology within this data set." (PMID 35039644, 2022).
squamous cell carcinoma (continued). "Tumor epithelial clusters expressed canonical squamous carcinoma markers such as CLDN1, LAMB3, TP63, CDKN2A, EPCAM, and SERPINB2, validating their malignant identity, while stromal and immune subsets displayed expected transcriptional programs." (PMID 41510303, 2025). "For instance, TP63 and SOX2 bind to the SEs and promoter of CCAT1, driving its expression and thereby activating the oncogenic EGFR pathway in squamous cell carcinoma." (PMID 39964764, 2025). "The CRC driven by tumor protein p63 (TP63), KLF5, and SREBF1 leads to the high expression of the methionine transporter L-type amino acid transporter 1 (LAT1) in squamous cell carcinoma, significantly promoting the accumulation of methionine within the cells." (PMID 40032852, 2025). "ML identified robust predictive models, highlighting SUV and kurtosis (from PET and CT features, respectively) and the expression levels of TP63, EPHA10, FBN2, and IL1RAP as key tools for distinguishing adenocarcinoma from squamous cell carcinoma." (PMID 40192792, 2025). "TP63 and WT1 are also prominently expressed in squamous cell carcinoma, bladder cancer, breast cancer, and gastric cancer." (PMID 38794221, 2024). "Squamous cell carcinomas showed frequent genic amplification of CCND1 and SOX2 and/or TP63, while ERBB2, VEGFA, GATA4, and GATA6 were more commonly amplified in adenocarcinomas." (PMID 37893095, 2023). "ΔNp63α, a splice isoform of TP63, induces the expression of GAPDH in squamous cell carcinoma when phosphorylated." (PMID 35886000, 2022). "To confirm in vivo that PTBP1 binds to TP63 pre-mRNAs, we immunoprecipitated specifically PTBP1/RNA complexes from keratinocytes (HaCaT) or squamous cell carcinomas cell lines (SCC9) cell extracts and analyzed the pre-mRNA content of the complexes by RT-PCR." (PMID 36970727, 2022). "LINC01503, which is regulated by SE and TP63, activates ERK and AKT pathways to promote the progression of squamous cell carcinoma." (PMID 35982471, 2022). "It has been reported that TP63 and SOX2 cooperatively regulate lncRNA CCAT1 expression by activating its SE and promoter in squamous cell carcinoma." (PMID 35982471, 2022). "On the other hand, TP63 facilitates squamous cell carcinoma (SCC) formation and an in vivo deletion of the TP63 gene in established SCC tumours leads to rapid tumour shrinkage, revealing a crucial function for TP63 in SCC maintenance." (PMID 34680271, 2021). "Due to IRF6 was known to be a target gene of TP63 in skin development and squamous cell carcinomas, we firstly attempted to analyze the co-expression of IRF6 and TP63 in human gastrointestinal tissues." (PMID 31019894, 2019). "Squamous cell carcinomas showed frequent genomic amplifications of CCND1 and SOX2 and/or TP63, whereas ERBB2, VEGFA and GATA4 and GATA6 were more commonly amplified in adenocarcinomas." (PMID 28052061, 2017). "Only two of the WT1 positive cancers were positive for CA125/MUC16, and only 3 of the TP63 positive samples expressed CK17 and CK5, characteristic of squamous carcinoma." (PMID 25885340, 2015). "In adult epithelial stem cells TP63 is a master regulator for the proliferative potential of these cells and interacts with SOX2 in squamous cell carcinomas." (PMID 25531390, 2014). "In addition, Studies have demonstrated that SREBF1 forms a reciprocal regulatory loop with TP63/KLF5 to promote survival and migration in squamous cell carcinoma." (PMID 40668814, 2025).
squamous cell carcinoma (continued). "In particular, squamous cell carcinoma (SCC) specific SE regions are cooperatively occupied with TP63 and SOX2 to boost CCAT1 seRNA transcription, CCAT1/TP63/SOX2 complex is bound to SE regions of epidermal growth factor receptor (EGFR) to promote EGFR transcription." (PMID 32278350, 2020). "In line with previous observations, this analysis showed that both adenocarcinomas and squamous cell carcinomas exhibited upregulation of pathways controlling cell differentiation, adhesion and immune responses, along with higher expression of ERBB2 and TP63 (Q < 0.05, Methods section)." (PMID 29535388, 2018). "The selected NSCLC PDX tumors were either histologically categorized as adenocarcinoma (Lu7406) or squamous cell carcinoma (Lu7414, Lu7177, Lu7766, and Lu7860), which was confirmed by the TP63 expression analysis with the exception of false-negative detection for Lu7414." (PMID 35039644, 2022). "Moreover, previous studies have shown that ACTL6A is coamplified with TP63 and may induce regenerative proliferation through the activation of YAP/TAZ in squamous cell carcinoma and glioma." (PMID 31504061, 2019). "Their combined radiogenomic model for predicting histotype (squamous cell carcinoma or adenoma) contained the same two genes (HIF1A and TP63) as their best model based on genes alone and no radiomic features." (PMID 35742947, 2022).